MIR124-1HG (MIR124-1 host gene)
Synonyms: Rncr3; neuroLNC; LINC00599
Gene: Long non-coding RNA gene on chromosome 8 (9,899,744 to 9,919,233, reverse strand). Ensembl gene ENSG00000253230.
Gene Ontology:
Biological process: miRNA-mediated post-transcriptional gene silencing
Cellular component: RISC complex
Diseases named in the same sentence as MIR124-1HG in open-access papers:
MIR124-1HG is named in the same sentence as 18 diseases in open-access papers, as found by Europe PMC text mining. Sharing a sentence is not in itself a finding about the gene and the disease. The quoted sentences say what the papers report.
diabetes (2 papers, 2017 to 2022). "Retinal Non-Coding RNA 3 (RNCR3), also known as MIR124-1HG (MIR124-1 Host Gene), is located on the chromosome 8p23.1 and has been firstly studied in diabetes-related microvascular abnormalities." (PMID 36290744, 2022).
MIR124-1HG also shares sentences with these, for which no sentence is quoted: atherosclerosis (16 papers); tumor (13); glioma (6); Hypercholesterolemia (5); colorectal cancer (4); prostate carcinoma (4); cancer (3); glioblastoma (3); neurodevelopmental disorder (2); Atherosclerotic lesion (1); behavioral variant frontotemporal dementia (1); brain cancer (1); diabetic retinopathy (1); hepatocellular carcinoma (1); hyperlipidemia (1); microcephaly (1); neurological disorders (1).